S100B (S100 calcium binding protein B)
Diseases named in the same sentence as S100B in open-access papers (continued):
Sharing a sentence is not in itself a finding about the gene and the disease.
inflammation (8 papers, 2012 to 2025). Aberrant reaction of the microcirculation characterized by movement of fluid and leukocytes from the blood into extravascular tissues. "Four days of IA LPS exposure causes a decreased PGP9.5- and S100β-positive surface area in the myenteric plexus along with submucosal and mucosal intestinal inflammation that coincided with systemic inflammation." (PMID 32883198, 2020). "Studies have found that H2S levels are correlated with peripheral pro-inflammatory cytokines (e.g. IL-6, S100B), suggesting its potential role in systemic inflammation." (PMID 40761437, 2025). "In conclusion, intestinal inflammation is associated with an overexpression of TRPV1 and S100β in enteric glia and astrocytes along the gut–brain axis, which is involved in pain establishment." (PMID 34829900, 2021). "Several studies have shown that S100B immunoreactivity mostly colocalizes with the GFAP-positive enteroglial mucosal network in tissue specimens from patients with intestinal inflammation." (PMID 24790767, 2014). "Intestinal inflammation is partly driven by enteroglial-derived S100B protein." (PMID 23259641, 2012).
metabolic disorders (5 papers, 2018 to 2025). "This analysis will allow for the examination of potential quantitative and qualitative relationships between NE, NSE, and S100B levels and standard indicators of inflammation, metabolic disorders, and clinical parameters." (PMID 39519343, 2024). "S100B is thought to mediate neuroinflammation and contribute to both AD pathogenesis and systemic inflammation seen in metabolic disease." (PMID 29681765, 2018).
infectious disease (3 papers, 2011 to 2023). A disorder directly resulting from the presence and activity of a microbial, viral, or parasitic agent in humans. "Interestingly, serum S100B was found to be increased in patients with cerebral and extracerebral infectious disease." (PMID 21970823, 2011).
peripheral neuropathy (3 papers, 2022 to 2024). A disorder affecting the peripheral nervous system. "Many biomarkers are being studied currently, including TNF-like weak inducer of apoptosis (TWEAK), lipocalin 2 (LCN2, an iron transporter in innate immunity), S100B (strongly associated with peripheral neuropathy), and brain-derived neurotrophic factor (BDNF)." (PMID 38893713, 2024). "Serum S100B levels were elevated in patients with T2DM with peripheral neuropathy, and S100B levels correlated with cognitive performance in patients with T2DM." (PMID 38396891, 2024).
adenocarcinoma (2 papers, 2018 to 2022). A common cancer characterized by the presence of malignant glandular cells. "In adenocarcinoma patients, S100B mRNA expression level was associated with better OS." (PMID 29607329, 2018).
bacterial infections (2 papers, 2009 to 2016). "To summarize, the present investigation provides a new perspective for the clinical study of S-100B, with special reference to neurologic sequelae after bacterial infections." (PMID 19814795, 2009). "Furthermore, S100B quantification in patients suffering from severe bacterial infections involving TLR2 activation might be relevant." (PMID 27047454, 2016).
cardiac disease (2 papers, 2015 to 2024). "To better understand the differential role of S100B in the interaction between cardiac disease and CNS, we here provide a comprehensive analysis of S100B in 146 HF patients, who underwent cognitive testing in the context of the Cognition.Matters-HF study." (PMID 39201780, 2024).
gastrointestinal disorders (1 paper, 2017). "Structural and functional alterations in enteric glia cells, such as the increase in S100β, have been described in animal models of stress-associated gastrointestinal disorders as well as in IBS patients." (PMID 28732069, 2017).
hematological disease (1 paper, 2011). "Genotype frequencies of the remaining RAGE and S100B polymorphisms were comparable among patients, donors and healthy individuals and were not significantly different with regard to the underlying hematological disease or antifungal prophylaxis." (PMID 22114731, 2011).
kidney (1 paper, 2019). "Furthermore, NF-κB p65 inhibitor PDTC enhanced the expression of S100B-induced SDF-1α in VSMCs, which was different from the role of activated NF-κB p65 by RAGE in inducing SDF-1α expression in the diabetic kidney." (PMID 31547879, 2019).
S100B also shares sentences with these, for which no sentence is quoted: amyotrophic lateral sclerosis (14 papers); concussion (11); liver cirrhosis (5); Brain atrophy (4); endothelial dysfunction (4); Atrophy (3); autism spectrum disorder (3); Coma (3); end-stage renal disease (3); frontotemporal dementia (3); Parkinson (3); type 1 diabetes (3); acute coronary syndrome (2); acute myocardial infarction (2); anemia (2); central nervous system diseases (2); cerebral palsy (2); CNS tumors (2); cognitive disorder (2); congenital heart disease (2); generalized anxiety disorder (2); gestational diabetes (2); Hypercholesterolemia (2); immune diseases (2); Impaired glucose tolerance (2); insomnia (2); kidney disease (2); periventricular leukomalacia (2); prostate carcinoma (2); Retinal (2).
A further 124 diseases each share a sentence with S100B in 2 papers or fewer.